SP1 (Sp1 transcription factor)
Diseases named in the same sentence as SP1 in open-access papers (continued):
Sharing a sentence is not in itself a finding about the gene and the disease.
breast carcinoma (continued). "The activity of the human SPARC promoter requires a purine-rich region with GGAGG repeats (within the -120/-70 fragment) in human breast cancer MCF7 cell line, and the transactivation of the SPARC promoter is dependent on the transcription factor Sp1/3 in Drosophila SL2 cells." (PMID 20687958, 2010). "In addition, SP1 is a potent transactivator of IGF-IR and EGFR, two prominent genes overexpressed in breast cancer cells (for example, MDA-MB-468) and both of which were identified as hits in our screen." (PMID 20576088, 2010). "Another limitation is that, although we demonstrated that patients with lung metastasis exhibit higher expression levels of SP1 in primary lesions, the present study has not identified a correlation between exosomal SP1 and metastasis status in breast cancer patients." (PMID 39630109, 2025). "In addition, the level of SP1 in TDEs increases, which favors the secretion of IL‐1β by neutrophils through the activation of the TLR4‐NFκβ pathway, ultimately aggravating lung metastasis of breast cancer." (PMID 39630109, 2025). "Particularly in breast cancer, SP1-induced overexpression of lncRNA AGAP2-AS1 upregulates MyD88 expression and activates the NF-κB signaling pathway by binding to the transcriptional coactivator CBP, which promotes breast cancer growth and enhances trastuzumab resistance." (PMID 40384875, 2025). "Further mechanistic studies revealed that ZN444B inhibits Fos-related antigen-2 (FOSL2) expression in breast cancer cells by inducing the disassociation of HDAC1 and Sp1, inhibits the deacetylase activity of HDAC1 on Sp1 at K703, and abrogates the binding ability of Sp1 to the FOSL2 promoter." (PMID 39010083, 2024). "Furthermore, in several breast cancer cell lines, RGZ activated the human Fas ligand (FasL) promoter in a PPARγ-dependent manner, increased the binding of PPARγ with Sp1 to the Sp1 sequence located within the FasL promoter, and positively regulated FasL expression." (PMID 36611922, 2022). "What is more, SP1 knockdown could partially abrogate the induction effect of ursolic acid on both Cav-1 protein expression and CAV1 promoter activity in breast cancer cells." (PMID 34568078, 2021). "Moreover, treatment of penfluridol with A549 cells did not inhibit or slightly enhanced the expression of Sp1, Sp3, and Sp4, suggesting the underlying mechanisms involved in the anticancer action of penfluridol in NSCLC and breast cancer are different." (PMID 31308361, 2019). "To this end, we examined the METABRIC breast cancer dataset for the expression of a signature composed of the genes belonging to the IL-6 or the WNT non-canonical pathways characterized by in vivo binding of both STAT3 and SP1, as identified above, denominated the SP1-S3 signature." (PMID 30654518, 2019). "Additionally, in breast cancer cells, LRF/ZBTB7A has been proposed to participate in transforming growth factor beta (TGF-β) signaling, a critical pathway for tumor progression, by binding to specificity protein 1 (SP1) and downregulating Smad4 expression." (PMID 31823818, 2019). "Interestingly, it has been reported in colon, gastric, pancreatic, and breast cancers that SP1 is overexpressed, whereas minimal‐to‐no SP1 expression is detected in normal differentiated cells." (PMID 29738634, 2018). "Moreover, quantitative analysis demonstrated that the double knockdown of Sp1 and Smad3 triggered an additive effect on EGFR expression in breast cancer cells but did not cause a synergistic effect." (PMID 29215776, 2018). "Taken together, our studies have demonstrated essential role of ERα and STAT5b in EGF/EGFR induced activation of PRLR gene transcription/expression in breast cancer cells via STAT5b interaction with ERα and complex formation with Sp1/C/EBPβ at the PRLR promoter in the absence of estrogen." (PMID 27564112, 2016).
breast carcinoma (continued). "Clinical evidences showed that Sp1 is over-expressed in a number of cancers and have been show to correlate with cancer cell migration and metastasis via the regulation of EMT in various cancers, such as gastric, pancreatic, breast cancers and hepatocellular carcinoma." (PMID 27829234, 2016). "However, this Sp1 element, which corresponds to Sp1-60 in this study, did not seem to promote the repressive action of estrogen in breast cancer cells." (PMID 27764788, 2016). "Another possible important mechanism involved is the Sp1/Sp3 binding sites and their regulatory effect on VEGF activity has been shown in some other cancers, such as the up-regulation of VEGF by oestrogen in breast cancer cells via the Sp1/Sp3 transcription sites in the core VEGF promoter." (PMID 26814431, 2016). "Also, MCF7 breast cancer cells that express caveolin-1 demonstrate much higher levels of IGF-IR gene promoter activity, and the effects of caveolin-1 on the IGF-IR gene promoter were mediated through Sp1." (PMID 25884514, 2015). "Ten base pairs away from this Sp-1 site is an ER binding site and the Sp-1 and ER transcription factors can interact so that the highest levels of MDM2 mRNA and protein are produced in cells that are G/G homozygotes and ER+ and exposed to estrogen as shown in breast cancer cells in culture." (PMID 20111735, 2010). "Additionally, Sp1/Sp3 binding sites located in the core promoter are known to play a role in transcriptional regulation of VEGF in a variety of cell lines including NIH3T3 cells, ZR-75 breast cancer cells, Y79 retinoblastoma cells, NCI-H322 bronchioloalveolar cells, and PANC-1 pancreatic cells." (PMID 23369005, 2013). "EGR and NFkB and SP1 in breast cancer have been reported to induce the mRNA expression of IFNGR, while AP2 in breast cancer and IRF2-mediated negative feedback in esophageal cancer have suppressive roles." (PMID 37275859, 2023). "Notably, Sp1 and Sp3 exist in distinct complexes and do not co-occupy the Sp1/3 site in the upstream promoter region of the trefoil factor 1 gene in MCF-7 breast cancer cells." (PMID 40869407, 2025). "Taken together, our studies have demonstrated an increase in expression of PRLR receptors in breast cancer cells induced by endogenous PRL/PRLR action via STAT5 interaction with pERα and complex formation with Sp1/C/EBPβ at the PRLR promoter in the absence of estrogen." (PMID 25193864, 2014). "The presence of SP1 together with IL2 signaling regulators, IGFBP2, IMPDH2 and HTT in separate subnetworks that excludes RAC signaling component might indicate the presence of at least two non-redundant mechanisms in P-inter breast cancers that may determine patient outcomes." (PMID 26257336, 2015).
gastric cancer (134 papers, 2009 to 2025). A primary or metastatic malignant neoplasm involving the stomach. "SP1 can up‐regulate the expression level of lncRNA LINC00659 to promote the tumor progression of gastric cancer through mir‐370‐AQP3 axis, which was associated with lymph node metastasis and poor prognosis." (PMID 38352696, 2024). "Previous studies have shown that multiple cancers were associated with overexpression of SP1, such as gastric cancer, pancreatic ductal adenocarcinoma, and lung cancer." (PMID 36964266, 2023). "Efp caused degradation of SP1, and high expression of Efp was related to the favorable prognosis of gastric cancer patients." (PMID 35954308, 2022). "In gastric cancer, Efp was found to cause poly-ubiquitination of specific protein 1 (SP1), a transcription factor that induces transcription of proteins including matrix metalloproteinases 2 (MMP2) and is involved in tumor growth, metastasis, and angiogenesis." (PMID 35954308, 2022). "The increased Sp1 expression was observed in several types of cancers, including lung cancer, pancreatic cancer, colon cancer, gastric cancer, and glioma cancer, and is associated with a poor prognosis in some cancers." (PMID 31783675, 2019). "Several have already been linked to cancer; for example SP1 is a prognostic factor for lower survival in gastric cancer, PRDM1 to be a tumor suppressor in lymphomas and YY1 as an initiator of tumorigenesis in several malignancies." (PMID 31337866, 2019). "Above results demonstrated overexpression of FEZF1-AS1 is mechanistically linked to increased gastric cancer cell proliferation via dependence on SP1." (PMID 28209170, 2017). "In a previous study, the abnormally activated Sp1 expression was shown to represent a potential risk for poor prognosis and directly caused gastric cancer progression." (PMID 23403540, 2013). "In summary, we determined that the level of SP1 expression exhibits different patterns in each of Lauren's histological types of human gastric cancers and is closely associated with patient survival." (PMID 23437057, 2013). "SP1 was reported to be associated with poor prognosis in gastric cancer and recently also in pancreatic ductal adenocarcinoma." (PMID 22615549, 2012). "To further determine whether the regulation of GABPA binding capacity by Sp1 depends on the TERT promoter mutations, we knocked down Sp1 in gastric cancer cell line AGS and colon cancer cell line RKO carrying BRAFV600E mutation and wild-type TERT promoter." (PMID 33483600, 2021). "To evaluate whether the loss of viability in the gastric cancer cell lines was indeed due to a reduction in Sp1, we treated cells with a known chemical inhibitor of Sp1, mithramycin (25 -200nM)." (PMID 28192510, 2017). "In gastric cancer (GC), SP1 was found to be associated with oncogenesis and to promote cancer cell growth and metastasis." (PMID 33579314, 2021). "SP1 is significantly overexpressed in gastric cancer, meningioma, lung adenocarcinoma, liver cancer, and pancreatic cancer." (PMID 40282196, 2025). "SP1 is overexpressed in various cancers, including gastric cancer, colorectal cancer, and lung cancer, and is positively correlated with tumor progression." (PMID 39749324, 2024). "For example, SP1 transcriptionally activated long non-coding RNA THAP7-AS1 to mediate gastric cancer progression." (PMID 38589918, 2024).
gastric cancer (continued). "In gastric cancer as well, transcription factor SP1 is an independent prognostic factor since it has been observed that the higher the expression of SP1, the higher the microvessel density (MVD) of the tumor." (PMID 38639888, 2024). "For instance, cytotoxin-associated gene A (CagA), a major virulence factor in Helicobacter pylori, promotes the progression of gastric cancer through the miR-155-5p/SMAD2/SP1 axis." (PMID 38689341, 2024). "RNA demethylase FTO promotes gastric cancer tumorigenesis and progression via the SP1-AURKB-ATM signaling pathway, shedding new light on the diagnoses and treatments for gastric cancer patients." (PMID 38956367, 2024). "MTA2 expression is regulated by the transcription factor Sp1 in gastric cancer and is capable of promoting the migration and invasion of gastric cancer cells." (PMID 37371463, 2023). "For example, SP1 activated LINC00659 in gastric cancer, promoting tumor progression by miR-370/aquaporin 3 (AQP3) axis." (PMID 37686205, 2023). "For example, miRNA-375, miRNA-375-3p, miRNA-1224-5p, miRNA-382, and miRNA-149 target Sp1 and decrease expression of Sp1 in colorectal cancer and eight miRNAs decrease Sp1 expression in gastric cancer." (PMID 36982239, 2023). "Meta-analysis of multiple studies has also been used to probe the role of Sp1 in gastric cancer, and higher Sp1 expression is correlated with increased depth of invasion and lymph node metastasis, increased TNM staging and Lauren’s classification." (PMID 36982239, 2023). "This aligns with the observation that in gastric cancer, where SP1 levels are high, MMRN1 levels are downregulated." (PMID 35132992, 2022). "For instance, lncRNA THAP7-AS1, which exerts oncogenic functions in gastric cancer, was transcriptionally activated by SP1 and then stabilized by METTL3-mediated m6A modification." (PMID 36309694, 2022). "SP1 is shown to transcriptionally regulate oncostatin M receptor in gastric cancer and thereby contribute to cancer progression." (PMID 36033825, 2022). "JWA inhibits the metastasis of melanoma and gastric cancer cells by inhibiting the expression of the transcription factor SP1 and intergrin αvβ3 through suppressing the ILK and MMP2 signaling pathways." (PMID 36230577, 2022). "The transcription factor specificity protein 1 (SP1) is overexpressed in many cancers, including gastric cancer, and modulates cell proliferation and survival." (PMID 35132992, 2022). "In gastric cancer, it has been documented that SP1 binds to the promoter regions of lncRNA AGAP2‐AS1 and promotes the transcriptional activity of this oncogenic lncRNA." (PMID 34185412, 2021). "In HCC, gastric cancer, pancreatic cancer and esophageal cancer, patients with increased SP1 were more likely to have poor outcomes (HR = 1.95; 95% CI: 1.16-3.28; p < 0.05)." (PMID 34257529, 2021). "SP1 knockdown was shown to decrease C1GalT1 expression while SP1 overexpression increase C1GalT1 expression in gastric cancer cells." (PMID 34944925, 2021). "Elevated SP1 expression was connected with shorter survival time of patients with hepatocellular carcinoma, pancreatic cancer, gastric cancer and esophageal cancer (HR = 1.95; 95% CI: 1.16-3.28; p < 0.05)." (PMID 34257529, 2021). "We concluded that enhanced SP1 expression was positively associated with unsatisfactory prognosis of various types of cancers including HCC, gastric cancer, pancreatic cancer and esophageal cancer (HR = 1.95; 95%CI:1.16-3.28; p < 0.05)." (PMID 34257529, 2021). "In gastric cancer cells, the specificity protein 1 (SP1) was shown to bind ANO1 promoter and recruit the mixed lineage leukemia MLL1 protein to promoter region, facilitating histone H3K4 trimethylation, and subsequently promoting ANO1transcription." (PMID 33250781, 2020). "Specificity factor 1 (SP1), previously shown to modulate invasion in breast, prostate, and gastric cancers, was differentially expressed in eaFTC and wiFTC compared with normal (p<0.05)." (PMID 33063251, 2020).
gastric cancer (continued). "Sp1 (specificity protein 1) is a cancer-associated transcription factor, and the level of Sp1 was significantly increased in parallel to the SENP3 level in gastric cancer cell lines, nude mice, and specimens derived from gastric cancer patients." (PMID 33192553, 2020). "It was found that TNPO2 was downregulated in gastric cancer cells at both mRNA and protein expression levels after SP1 knockdown." (PMID 31605449, 2019). "Next, SP1 was knocked down in gastric cancer cells with the aim to detect altered TNPO2 mRNA and protein expression levels." (PMID 31605449, 2019). "In this study, analysis of TCGA and KmPlotter data also showed that high expression of ZEB2 or Sp1 is correlated with poor survival of colorectal and gastric cancer patients." (PMID 29416649, 2018). "Further, inhibition of Sp1 (by mithramycin) in gastric cancer cell lines resulted in downregulation of HSF1 and HSP70 expression as well." (PMID 28192510, 2017). "High Sp1 expression in tumor specimens has been correlated with reduced postoperative survival of gastric cancer patients, possibly indicating a prognostic role of Sp1." (PMID 28192510, 2017). "As the member of Sp family, Specificity Protein 1 (Sp1) is overexpressed in a variety of cancers, such as gastric cancer, pancreatic cancer, and prostate cancer, and is closely associated with poor prognoses of cancers." (PMID 29262634, 2017). "Sp1 inhibition has been shown to exert anti-proliferative, anti-migration and anti-invasion effects on gastric cancer cells." (PMID 28192510, 2017). "The overexpression or constitutive activation of SP-1 has shown to be involved in tumor development and metastasis of cancer cells, including brain tumor astroglioma and gastric cancer and lung cancer." (PMID 28286419, 2017). "The TF SP1 also identified with the highest occurrences; it is highly expressed in the tumor cells progression of gastric cancer." (PMID 28871224, 2017). "Collectively, these results indicate that decreased expression of transcription factor Sp1 contributes to suppression of SHIP2 in gastric cancer cells." (PMID 28117748, 2017). "Analysis of transcriptional activity of SHIP2 promoter revealed Specificity protein 1 (Sp1) was responsible for the regulation of SHIP2 expression in gastric cancer cells." (PMID 28117748, 2017). "Our results showed that overexpression of Sp1 rescued the gastric cancer cells from triptolide induced cell death." (PMID 28192510, 2017). "As a candidate risk factor for gastric cancer, glucose-derived AGEs can promote gastric cancer cells invasion and metastasis via RAGE/ERK/Sp1/MMP2 pathway." (PMID 29262634, 2017). "In gastric cancer cells, triptolide, at a concentration of 100nM decreased the mRNA expression of Sp1 at 24 hours and 48 hours of treatment in both MKN45 and MKN28 cells." (PMID 28192510, 2017). "Our study indicates that like pancreatic cancer, triptolide inhibits Sp1 in gastric cancer as well to downregulate HSP70 and HSF1 to induce cell death." (PMID 28192510, 2017). "In gastric cancer cell lines and specimens derived from patients and nude mice, the level of Sp1 was generally increased in parallel to the level of SENP3." (PMID 26511642, 2016). "Together with the biochemical and molecular biological data generated in cultured cells, these results have provided a novel regulatory mechanism to explain the overexpression of Sp1 in gastric cancers at the post-translation level." (PMID 26511642, 2016). "We herein show a close correlation between the protein levels of SENP3 and Sp1 in the patient’s gastric specimens, as well as in the nude mouse xenografts of human gastric cancers." (PMID 26511642, 2016). "In the present study, we have shown that H2O2 treatment leads to an increase of Sp1 in the gastric cancer cell line, which is dependent on an induction of SENP3." (PMID 26511642, 2016).